CD300A (CD300a molecule)
Diseases named in the same sentence as CD300A in open-access papers (continued):
Sharing a sentence is not in itself a finding about the gene and the disease.
melanoma (1 paper, 2021). A malignant, usually aggressive tumor composed of atypical, neoplastic melanocytes. "We also show that higher expression of CD300A was associated with decreased tumor-infiltrating Treg cells and longer survival time in patients with melanoma." (PMID 34751648, 2021). "In contrast, Rag-deficient (Rag1−/−) and Rag1−/−;Cd300a−/− mice showed comparable levels of tumor development and survival after injection of B16 melanoma cells." (PMID 34751648, 2021). "Indeed, we showed that higher expression of CD300A was associated with lower expression of Foxp3 and longer survival times of melanoma patients." (PMID 34751648, 2021). "CD300A expression associates with survival of human melanoma patients." (PMID 34751648, 2021). "Here, we found that mice deficient in the inhibitory immunoreceptor CD300a on their dendritic cells (DCs) have increased numbers of Treg cells in tumors and greater tumor growth compared with wild-type mice after transplantation of B16 melanoma." (PMID 34751648, 2021). "Though human CD300A is reported to be expressed on the subsets of T cells in peripheral blood, human melanoma tissues showed quite low CD300A expression in T cells compared to high expression in the myeloid cells." (PMID 34751648, 2021). "To identify the CD300a-expressing myeloid cell population that is involved in melanoma suppression, we used Cd300afl/fl;ItgaxCre and Cd300afl/fl;Lyz2Cre mice." (PMID 34751648, 2021). "The Cd300a−/− mice showed larger tumor volume and shorter survival than did wild-type mice, indicating that CD300a suppresses the development of melanoma." (PMID 34751648, 2021). "(G and H) Comparison of tumor growth and survival curves of B16 melanoma cells between ticam-1−/− (n = 6) and ticam-1−/−;Cd300a−/− ice (n = 9) after inoculation of B16 melanoma." (PMID 34751648, 2021). "(I and J) Comparison of tumor growth and survival curves of B16 melanoma between MyD8−/− (n = 9) and MyD88−/−;Cd300a−/− mice (n = 10) after inoculation of B16 melanoma." (PMID 34751648, 2021). "(A and B) Quantitative everse transcription PCR (RT-PCR) analysis of mRNA from CD11c+ cells sorted from B16 melanoma in wild-type (WT), Cd300afl/fl (n = 6), Cd300a−/− or Cd300afl/fl;ItgaxCre (n = 6) mice 2 weeks after tumor inoculation." (PMID 34751648, 2021). "However, Cd300a−/− BMDCs showed decreased Ifnb expression to a level comparable to wild-type BMDC when these BMMCs were cultured in the culture supernatants of B16 melanoma cells after removal of TEVs by phosphatidylserine receptor-conjugated beads." (PMID 34751648, 2021). "We purified TEVs from the culture supernatants of B16 melanoma cells by centrifugation and phosphatidylserine receptor-conjugated beads, which indeed expressed phosphatidylserine on the surface and bound to a chimeric fusion protein of the extracellular portion of CD300a with human IgG1." (PMID 34751648, 2021).
myocardial infarction (1 paper, 2025). Gross necrosis of the myocardium, as a result of interruption of the blood supply to the area, as in coronary thrombosis. "To examine whether CD300a is involved in the pathogenesis of cardiac IRI, we established a murine model of myocardial infarction and reperfusion (MI/R) by the occlusion of the left anterior descending artery for 1 hour followed by arterial reperfusion." (PMID 40705472, 2025).
non-small cell lung carcinoma (1 paper, 2025). A group of at least three distinct histological types of lung cancer, including non-small cell squamous cell carcinoma, adenocarcinoma, and large cell carcinoma. "In non-small cell lung cancer (NSCLC), the expression of CD300a is elevated, and its high expression is negatively correlated with NSCLC tumor suppression, potentially through inhibition of the Wnt/β-catenin signaling pathway, thereby slowing tumor progression." (PMID 40507267, 2025).
osteoarthritis (1 paper, 2024). A noninflammatory degenerative joint disease occurring chiefly in older persons, characterized by degeneration of the articular cartilage, hypertrophy of bone at the margins and changes in the synovial membrane. "Further data analysis validated that these genes (TK1, CD300A, EGFR, and UTY) are correlated with the immune microenvironment of Osteoarthritis." (PMID 38549939, 2024). "We used deep machine learning algorithms, including the LASSO and SVM algorithms, to identify four candidate feature genes in Osteoarthritis cases: TK1, CD300A, EGFR, and UTY." (PMID 38549939, 2024). "However, the roles of TK1, CD300A, and UTY in Osteoarthritis have not yet been reported." (PMID 38549939, 2024).
peanut allergy (1 paper, 2022). "We used our model of the effector phase of peanut allergy to assess the impact of engaging inhibitory receptors CD300a and Siglec-8 on peanut-induced effector cell activation." (PMID 36248809, 2022).
pertussis (1 paper, 2021). A contagious bacterial respiratory infection caused by Bordetella pertussis. "In the PT2 infants, central memory CD8T cells (CD300a MFI) increased 2.2 fold with pertussis and 1.02-fold, increased, central memory CD8 T cells (TNF-α MFI) and BCMA+ plasma cells raised 1.5-fold with HBsAg while central memory CD8 T cells (CD300a MFI) increased 2.33 fold for HiB." (PMID 33968011, 2021).
pneumonia (1 paper, 2023). An acute, acute and chronic, or chronic inflammation focally or diffusely affecting the lung parenchyma, caused by an infection in one or both of the lungs (by bacteria, viruses, fungi, or mycoplasma.). "Importantly, CD300a might be a useful marker to easily analyze the frequency of IgM memory B cells in PLWH, which may allow us to predict a higher susceptibility to pneumonia or a lower vaccine response against pneumococcus in these patients." (PMID 37762055, 2023).
renal fibrosis (1 paper, 2025). A final common manifestation of a wide variety of chronic kidney diseases characterized by glomerulosclerosis and tubulointerstitial fibrosis. "Moreover, renal fibrosis at 28 days after biIRI was significantly milder in mice treated with the anti-CD300a mAb than in those treated with the control antibody." (PMID 40705472, 2025). "Using a 2-step uIRI, during the 49-day observation period, plasma BUN and creatinine concentrations were significantly lower, and the degree of renal fibrosis was significantly milder, in mice treated with the anti-CD300a mAb than in mice treated with the control antibody." (PMID 40705472, 2025).
skin cutaneous melanoma (1 paper, 2021). "(A) Kaplan plot showing low and high CD300A expressions in skin cutaneous melanoma (SKCM) patients obtained by performing a meta-analysis of The Cancer Genome Atlas (TCGA) database." (PMID 34751648, 2021). "We further analyzed the database of the Cancer Genome Atlas (TCGA) project and found that skin cutaneous melanoma (SKCM) patients expressing low levels of CD300A mRNA had shorter survival times than did those expressing higher CD300A mRNA levels." (PMID 34751648, 2021).
visceral leishmaniasis (1 paper, 2021). A severe form of leishmaniasis characterized by irregular bouts of fever, substantial weight loss, swelling of the spleen and liver, and anemia (which may be serious). "Taken together, our results suggest that CD300a signaling is detrimental to the quality and magnitude of phagocytic, APCs, and T cells effector functions in experimental visceral leishmaniasis caused by L. donovani." (PMID 35116028, 2021). "For the first time, we report that L. donovani, which causes visceral leishmaniasis in the Indian subcontinent, upregulates the expression of an immune inhibitory receptor i.e., CD300a on antigen presenting and phagocytic cells to dampen their effector functions." (PMID 35116028, 2021).
Zika Virus Infection (1 paper, 2024). "Overall, the presented data support the role of PS receptors TIM-1 and CD300a in ZIKV infection and provide insights into the possibility of developing PS inhibitors targeting this universal entry pathway." (PMID 39194591, 2024). "We also report for the first time that CD300a enhanced ZIKV infection, as has been previously shown for other Orthoflaviviruses as well." (PMID 39194591, 2024). "Here, we evaluate for the first time if CD300a is also involved in the in vitro ZIKV infection of HEK293T cells and monocyte-derived dendritic cells." (PMID 39194591, 2024). "In this study, we used CEI biosensor technology to study the role of the PS receptors TIM-1 and CD300a in in vitro ZIKV infection using overexpression and knockout cell culture models." (PMID 39194591, 2024).
tumor (20 papers, 2015 to 2025). "CD300a has been implicated in promoting tumor growth by modulating the PI3K-AKT signaling axis, particularly in early T-lineage lymphomas (ETTLs)." (PMID 40507267, 2025). "Although some of these findings are derived from in vivo models, the cumulative evidence positions CD300a as a critical immune checkpoint in tumor-associated immune regulation." (PMID 40507267, 2025). "Overexpression of CD300a in NK cells is associated with impaired anti-tumor activity, as demonstrated by decreased survival in xenograft mouse models, supporting the role of CD300a-mediated inhibition in tumor clearance by NK cells." (PMID 40507267, 2025). "Recent studies suggest that tumor cells may hijack CD300a-associated pathways to establish an immunosuppressive microenvironment that facilitates immune evasion, tumor survival, and potentially metastatic spread." (PMID 40507267, 2025). "In addition, compared with normal DCs, CD300A-deficient DCs produced more IFN-β after being treated with tumour-derived exosomes, thus increasing the tumour invasion of Tregs." (PMID 38302430, 2024). "Moreover, the tumor-specific mechanisms underlying CD300a-mediated immune inhibition are largely unknown." (PMID 40507267, 2025). "Ectopic CD300a expression in NK cells markedly reduces their cytotoxic activ-ity on hematologic tumor cells and promotes the in vivo progression of the tumor." (PMID 40507267, 2025). "Due to its wide expression on innate and adaptive immune cells, CD300a represents a compelling candidate for interventions in scenarios requiring selective modulation of immune responses or interrupting tumor-induced immunosuppression." (PMID 40507267, 2025). "In preclinical models, genetic deletion or functional inhibition of CD300a increase immune reactivity and limit tumor growth, further indicating its classification as an immune checkpoint." (PMID 40507267, 2025). "Beyond its role as a ligand for CD300a, externalized PS also acts as a broader immunoregulatory signal within the tumor microenvironment, where it modulates immune cell behavior and contributes to tumor immune evasion." (PMID 40507267, 2025). "Elevated CD300a expression on NK cells has been demonstrated to reduce their cytotoxicity against tumor cells." (PMID 40507267, 2025). "This review summarizes the current understanding of the immunoregulatory functions of CD300a in various immune cell types, with a particular focus on its role in tumor immune evasion." (PMID 40507267, 2025). "In summary, preclinical evidence to date is exciting, but additional detailed work is required to better characterize the multifaceted effects of CD300a engagement within diverse tumor microenvironments." (PMID 40507267, 2025). "In con-trast, the blockade of the CD300a-PS interaction by antibodies increases the transcription of cytotoxic proteins and cytokines in the NK cells, restoring their tumor-killing function." (PMID 40507267, 2025). "A large fraction of tumor-infiltrating immune cells expresses high levels of inhibitory receptors, including CD300a." (PMID 40507267, 2025). "Beyond allergic contexts, tumor cells expressing PS can also engage CD300a-mediated processes to inhibit mast cell degranulation and the release of cytokines." (PMID 40507267, 2025). "The control of tumor-infiltrating Treg cells and antitumor immunity is significantly influenced by EVs generated from tumor cells and CD300A of DCs." (PMID 36832253, 2023). "In particular, CD300A is also expressed on the tumor‐suppressive NK and CD8+ T cells, in which it mediates inhibitory signal and leads to an exhaustion status of these cell." (PMID 35642341, 2023). "The inhibitory receptor protein CD300A is found on leukocytes and is involved in the immune response signaling pathways; the interaction between CD300A and phosphatidylserine can inhibit the killing effect of natural killer (NK) cells on tumor cells." (PMID 36425064, 2022).
tumor (continued). "CD300a inhibits TLR3-mediated interferon-β (IFN-β) expression upon recognition of tumor-derived exosomes." (PMID 34751648, 2021). "To elucidate how CD300a on DCs enhances the adaptive immune response against tumor development, we analyzed the population of tumor-infiltrating Treg cells by use of flow cytometry and immunohistochemistry." (PMID 34751648, 2021). "Coculture of DCs with tumor-derived EV (TEV) induced the internalization of CD300a and the incorporation of EVs into endosomes, in which CD300a inhibited TEV-mediated TLR3–TRIF signaling for activation of the IFN-β-Treg cells axis." (PMID 34751648, 2021). "Our findings reveal the role of TEV and CD300a on DCs in Treg cell activation in the tumor microenvironment." (PMID 34751648, 2021). "In contrast to the barrier tissues, Cd300a−/− mice still showed larger numbers of Treg cells and a larger tumor volume than did wild-type mice raised under GF conditions." (PMID 34751648, 2021). "Our findings thus highlighted the role of TEV and CD300a on DCs in the regulation of tumor-infiltrating Treg cells and tumor immunity." (PMID 34751648, 2021). "Still, further work will be required to evaluate the importance of CD300a in regulating NK cell recognition of tumor cells in vivo." (PMID 34503073, 2021). "To summarize, we, for the first time, confirmed that CD300A promoted tumor progression by increase PECAM1 and ADCY7 expression, and activating the AKT/mTOR signaling pathway in AML." (PMID 29938007, 2018). "CD300a is an inhibitory receptor that can be expressed by NK cells and that deliver inhibitory signals upon binding to PS expressed by tumor cells." (PMID 27872625, 2016). "The loss of CD300A inhibited DLBCL cell proliferation in vitro and suppressed tumor growth in vivo, an effect likely mediated by its inhibition on PI3K/AKT activation." (PMID 26435477, 2015). "Quantitative PCR data revealed that the mRNA levels of CD300A were significantly greater in DLBCL tumor tissues than that in human benign lymphoid tissues." (PMID 26435477, 2015). "Collectively, our results clearly identified the high expression of CD300A in DLBCL tumor tissues and a novel oncogenic role of CD300A in DLBCL." (PMID 26435477, 2015). "In the present study, we found that the levels of CD300A in lymphoid tissues were greater in patients with DLBCL than that in patients with benign diseases." (PMID 26435477, 2015). "The results showed that downregulation of CD300A led to a profound suppression of tumor growth, as evidenced by a significant reduction in tumor volume and weight." (PMID 26435477, 2015). "Secondly, the binding affinity between CD300a and its ligands (PS and PE) may vary according to the type of membrane and the nature of tumor stress, thereby influencing immune evasion." (PMID 40507267, 2025). "In particular, the accessory mechanisms may involve: (i) the exposure of PS or PE on tumor cells, and/or (ii) the heterogeneous expression of CD300a across immune cell subsets within the TME." (PMID 40507267, 2025). "Nevertheless, whether CD300a exerts a direct functional role in tumor progression or immune evasion in these solid tumors remains speculative and should be interpreted with caution." (PMID 40507267, 2025). "Among them, CD300a is a prototypical inhibitory receptor, highly expressed in both myeloid and lymphoid lineages, and plays a pivotal role in the pathogenesis of inflammation and tumor immunity." (PMID 40507267, 2025). "PS was externalized on the surface of tumor cells, and CD300a bound specifi-cally to PS." (PMID 40507267, 2025). "First, the expression and role of CD300a on different tumor-infiltrating immune cell subsets are largely unknown." (PMID 40507267, 2025). "The function of CD300a in the regulation of neutrophils has been relatively well defined, but that of CD300f has not been well studied, particularly in the context of neutrophil-mediated tumor immunity." (PMID 40507267, 2025).